MCM4 (minichromosome maintenance complex component 4)
Description:
Acts as a component of the MCM2-7 complex (MCM complex) which is the replicative helicase essential for 'once per cell cycle' DNA replication initiation and elongation in eukaryotic cells. Core component of CDC45-MCM-GINS (CMG) helicase, the molecular machine that unwinds template DNA during replication, and around which the replisome is built. The active ATPase sites in the MCM2-7 ring are formed through the interaction surfaces of two neighboring subunits such that a critical structure of a conserved arginine finger motif is provided in trans relative to the ATP-binding site of the Walker A box of the adjacent subunit. The six ATPase active sites, however, are likely to contribute differentially to the complex helicase activity.
Synonyms: CDC21; CDC54; hCdc21; P1-Cdc21; MGC33310; IMD54; NKCD; NKGCD
Tractability: Small molecule: a structure with a bound ligand is known. PROTAC: UniProt records ubiquitination sites on it; ubiquitination databases record sites on it; its protein half-life has been measured; a small molecule that binds it is known.
Target class: Enzyme; Hydrolase
Gene: Protein-coding gene on chromosome 8 (47,960,185 to 47,978,165, forward strand). Ensembl gene ENSG00000104738.
Subcellular location: Nucleus; Chromosome
Subcellular location (Human Protein Atlas): Nucleoplasm
Pathways (Reactome):
DNA Replication: Activation of the pre-replicative complex; Assembly of the pre-replicative complex; Orc1 removal from chromatin; Switching of origins to a post-replicative state; Unwinding of DNA
Cell Cycle: Activation of ATR in response to replication stress
Gene Ontology:
Molecular function: ATP hydrolysis activity; DNA helicase activity; protein binding; single-stranded DNA binding; single-stranded DNA helicase activity; ATP binding; DNA binding
Biological process: DNA replication; DNA strand elongation involved in DNA replication; double-strand break repair via break-induced replication; mitotic DNA replication initiation; regulation of DNA-templated DNA replication initiation; DNA metabolic process; DNA replication initiation
Cellular component: chromosome, telomeric region; CMG complex; MCM complex; membrane; nucleoplasm; nucleus; chromosome
Genetic constraint (gnomAD): Loss-of-function variants: 46 observed, 72.94 expected, observed/expected ratio (o/e) 0.63, 90% interval 0.5 to 0.81. The upper end of that interval is the gene's LOEUF score, 0.81, which puts it in group 3 of 6, group 1 being the genes least tolerant of losing a copy. Missense variants: 968 observed, 970.13 expected, observed/expected ratio (o/e) 1, 90% interval 0.95 to 1.05. Synonymous variants: 393 observed, 365.12 expected, observed/expected ratio (o/e) 1.08, 90% interval 0.99 to 1.17.
Gene-disease validity (ClinGen):
ClinGen rates the evidence that MCM4 causes each of these diseases.
primary immunodeficiency with natural-killer cell deficiency and adrenal insufficiency (autosomal recessive): Moderate. The primary immunodeficiency with natural-killer cell deficiency and adrenal insufficiency is characterized by a specific natural-killer (NK) cell deficiency and susceptibility to viral diseases.
Homologues: Orthologues: chimpanzee MCM4 (99% identical), macaque MCM4 (99% identical), rabbit MCM4 (97% identical), guinea pig MCM4 (95% identical), rat Mcm4 (95% identical), mouse Mcm4 (95% identical), pig MCM4 (90% identical), tropical clawed frog mcm4 (86% identical), zebrafish mcm4 (80% identical), Drosophila melanogaster dpa (63% identical), Caenorhabditis elegans mcm-4 (52% identical). Paralogues in human: MCM5 (27% identical), MCM2 (27% identical), MCM3 (27% identical), MCM7 (25% identical), MCM6 (25% identical), MCM8 (25% identical), MCM9 (22% identical), MCMDC2 (13% identical).
Diseases named in the same sentence as MCM4 in open-access papers:
MCM4 is named in the same sentence as 127 diseases in open-access papers, as found by Europe PMC text mining. Sharing a sentence is not in itself a finding about the gene and the disease. The quoted sentences say what the papers report.
breast cancer (17 papers, 2010 to 2025). A primary or metastatic malignant neoplasm involving the breast. "Among MCM2‐7, MCM4 is considered as the most conservative protein, and its abnormal expression is associated with cancer progression, including mammary carcinoma, oesophageal and breast cancer." (PMID 37817427, 2023). "In breast cancer, high level of MCM4 expression was associated with disease progression, ER-negative or high-grade breast tumors, and shorter survival." (PMID 27476776, 2016). "Chaos3 mice, which are engineered with a point mutation in the minichromosome maintenance 4 (Mcm4) gene, are highly unstable genomically, leading to the development of mammary tumours which resemble human breast cancers." (PMID 25026295, 2014). "Additionally, the mutation MCM4 F345I has been found to be associated with breast cancer." (PMID 40959096, 2025). "MCM4 has recently been reported as a new prognostic biomarker in some cancers, including GC, breast cancer and hepatocellular carcinoma." (PMID 37737200, 2023). "Mcm4 abnormally expresses in tumors such as gastric cancer, esophageal cancer and breast cancer, and is a special marker of proliferating cells." (PMID 37198697, 2023). "MCM4 is high expression in breast cancer patient and silencing MCM4 significantly inhibited the proliferation of breast cancer cells." (PMID 37817427, 2023). "In contrast, MCM4 gene promoter was hypermethylated in breast cancer and BCL2, PIK3R1 gene promoter were hypomethylated." (PMID 31777591, 2019). "In our analysis, we identified that MCM2 and MCM4 are vital to the survival of breast cancer." (PMID 33816496, 2021). "The upregulated MCM4 gene in our result is one of the genes involved in DNA replication and cell cycle, it has been reported that mutation in MCM plays a role in cancer development in mice and may increase breast cancer risk in humans." (PMID 21060778, 2010). "Issac MSM and his colleagues indicated that the expression of MCM2, MCM4, and MCM6 was obviously increased in breast cancer compared to that in corresponding para-cancerous tissues." (PMID 34178669, 2021). "For instance, in breast cancer, MCM2, MCM4 and MCM6 can help distinguish breast cancers with different histological grades." (PMID 34859821, 2021).
melanoma (17 papers, 2009 to 2025). A malignant, usually aggressive tumor composed of atypical, neoplastic melanocytes. "In summary, our findings revealed a strong association between MCM4 expression and susceptibility to ferroptosis in melanoma cells." (PMID 39290263, 2024). "In summary, we detected elevated expression levels of MCM2–6 and MCM10 in melanoma and found that increased MCM4/5/10 mRNA levels were associated with a worse prognosis for patients with melanoma." (PMID 34490114, 2021). "Further immunohistochemical validation in FFPE melanomas revealed that two related genes, MCM4 and MCM6, were associated with patient MSS." (PMID 31360859, 2018). "Importantly, high expression of MCM4 was found to be highly associated with worse OS in patients with melanoma, and MCM4 had a positive correlation with B cells and T cells." (PMID 34490114, 2021). "MCM4 was reported to be a promising marker for distinguishing benign from malignant melanocytic skin lesions and to be associated with shorter survival in patients with melanoma." (PMID 27476776, 2016). "We further investigated the clinical impact of MCM4 expression on patient outcomes by analyzing data from seven melanoma cohorts in the TCGA-SKCM and GEO databases." (PMID 40959096, 2025). "The results demonstrated a marked increase in intracellular ROS levels in the A375 and B16F0 melanoma cell lines upon MCM4 depletion and subsequent treatment with the ferroptosis inducer erastin." (PMID 39290263, 2024). "We elucidated the potential of targeting MCM4 for melanoma treatment and demonstrated the anti-tumor efficacy both in vitro and in vivo." (PMID 39290263, 2024). "In this study, we reported that MCM4 is a promising target for melanoma-specific therapy, given its crucial role in regulating ferroptosis sensitivity in melanoma cells." (PMID 39290263, 2024). "We demonstrated the effect of MCM4 silencing on the sensitivity of melanoma cells to ferroptosis both in vitro and in vivo." (PMID 39290263, 2024). "The current study identified MCM4 as a potential target for melanoma therapy, as reducing MCM4 expression enhanced ferroptosis sensitivity in melanoma cells." (PMID 39290263, 2024). "A study reported that some melanoma patients with increased expression of MCM4 have a poor prognosis." (PMID 36465369, 2022). "The expression of MCM4 is related to the metastasis of melanoma, and related to the poor prognosis of melanoma patients." (PMID 34993142, 2021). "In this study, we found that the expression of MCM4 was higher in melanoma than in normal skin tissues." (PMID 34490114, 2021). "As a positive control, we included MCM4, which has been shown to be a poor melanoma survival gene in an independent study." (PMID 27689402, 2016). "We observed a similar difference in survival for MCM4 gene, previously reported as a prognostic marker in melanoma." (PMID 27689402, 2016). "In previous study, MCM2, MCM3 and MCM4 were dysregulated in malignant salivary gland tumours, gastric cardiac cancer, thyroid malignancy, non-small cell lung cancer, malignant melanoma, colon cancer, promyelocytic leukemia, cervical squamous cell carcinoma." (PMID 24386425, 2013). "In the melanoma group (n = 113), the median value of MCM4 positivity was 36.8% in contrast to 2.0% in nevi (n = 31) (p < 0.001, Mann-Whitney test)." (PMID 20398247, 2010). "In melanoma, the correlation coefficient was 0.318, with a p-value < 0.01, suggesting that MCM4 may contribute to the stemness characteristics of SKCM." (PMID 40959096, 2025). "Furthermore, we demonstrated that MCM4 silencing promoted the sensitivity of melanoma cells to ferroptosis both in vitro and in vivo." (PMID 39290263, 2024). "The upregulated MCM4/5/10 expressions could be used as potential prognostic markers to improve the poor outcome and prognostic accuracy in patients with melanoma." (PMID 34490114, 2021). "Therefore, MCM4 has been proposed as a novel ferroptosis target in melanoma treatment." (PMID 39290263, 2024).
melanoma (continued). "Moreover, significantly more MCM4 was expressed in melanoma compared with in-nevi tissue." (PMID 34490114, 2021). "Western blot results showed that silencing MCM4 led to reduced GPX4 expression in both human and murine melanoma cells." (PMID 39290263, 2024). "High mRNA levels of MCM4, MCM5, and MCM10 were closely related to worse prognosis in patients with melanoma." (PMID 34490114, 2021). "In malignant melanoma, gene expression analysis and independent immunohistochemical validation have uncovered several MCM family members, i.e. MCM3, MCM4 and MCM6 as biomarkers of poor prognosis." (PMID 22805320, 2012). "MCM4 combined with GMNN overexpression as found in our material, is also predictive for metastasis and poor survival in melanoma, documented in a large prospective microarray study." (PMID 19662092, 2009). "We further detected changes in ROS levels by the DCFDA probe in erastin-treated melanoma cells with or without MCM4 knockdown." (PMID 39290263, 2024). "We additionally confirmed the expression with mRNA levels of key genes after treatment with lj-1-59 in melanoma cells, which indicated that P21, BBC3, SESN2 and GADD45A expression were significantly upregulated, while MCM2, MCM3, MCM4, MCM7 and PKMYT1 were significantly downregulated." (PMID 32021565, 2020). "While we are not aware of any other validatory studies on the prognostic value of MCM3 expression in melanoma, a recent study failed to confirm the prognostic value of MCM4 in a consecutive cohort of nodular melanoma (n = 220)." (PMID 22805320, 2012).
cervical cancer (14 papers, 2013 to 2025). A primary or metastatic malignant neoplasm involving the cervix. "Recently, MCM4 is reported to have a complex interaction with multiple cancer progression, including gastric, ovarian and cervical cancer." (PMID 37817427, 2023). "In cervical cancer, bladder cancer, cutaneous melanoma, and oral squamous cell carcinoma, MCM4 and MCM7 have been reported to be promising prognostic markers for disease progression." (PMID 27476776, 2016). "However, the higher expression of MCM2, MCM4, and MCM6 is significantly associated with favorable overall survival in cervical cancer patients." (PMID 36765810, 2023). "The loss of MCM4 improved the therapeutic effect of cisplatin because of the induced DNA damage, indicating that MCM4 could be a potential cancer treatment target in cervical cancer." (PMID 34490114, 2021). "Meanwhile, the overexpression of MCM4, MCM5, MCM6, MCM10 and RECQL4 mRNA has been reported as a poor prognostic indicator in cervical cancer." (PMID 29463213, 2018). "Our data indicates the role of MCM4, MCM5, MCM6, MCM10 and RECQL4 in the progression of cervical cancer." (PMID 23874974, 2013). "MCM2 and MCM4 suppress CRC and HPV‐type of cervical cancer progression, respectively." (PMID 38988047, 2024). "In cervical cancer, MCM2 and MCM6 are upregulated while MCM4 is downregulated." (PMID 36765810, 2023). "Interestingly, levels of members of the Minichromosome Maintenance (MCM) family (MCM2, MCM3, MCM4, MCM5, MCM6, MCM7) were found to be highly significantly increased in cervical cancer tissue from early and late stage patients as compared to healthy tissue." (PMID 29719595, 2018). "Capitalizing upon and targeting Minichromosome maintenance protein complex - specifically the MCM2, MCM4 and MCM6 subunits, ZWINT and CDC7 for experimental validation, may provide valuable insights in understanding and detection of progressing cervical neoplasia to cervical cancer at an early stage." (PMID 30150654, 2018). "With this analysis, only MCM4 of the MCM2-7 family was observed in early and late stage cervical cancer and not detectable in healthy epithelium and stroma cells." (PMID 29719595, 2018). "MCM4, 5 and 6 also show differential expression in different types of lesion, while MCM2 and MCM10 are over expressed in cervical cancer irrespective of clinico-pathological parameters." (PMID 23874974, 2013).
lung cancer (11 papers, 2016 to 2025). A malignant neoplasm involving the lung. "Using the Lung Cancer Explorer platform, we observed that MCM4 expression was positively correlated with MMP9 and MMP12 across both TCGA and GSE32863 datasets, supporting a potential role of MCM4 in promoting ECM degradation and invasion." (PMID 40564876, 2025). "Upregulation of MCM4 was found to be a potential prognostic biomarker for lung cancers by coordinating the cell cycle, DNA replication, and other biological processes and pathways." (PMID 34490114, 2021). "In contrast, the higher the relative expression of MCM4 gene in older women, the more likely they were to have lung cancer (OR = 6.31)." (PMID 27418131, 2016). "MCM4 may play essential roles in proliferation and could be a potential therapeutic target in non‐small cell lung cancer." (PMID 37491836, 2023). "MTHFD2 was involved in lung cancer cell proliferation, migration, and apoptosis by mediating its downstream molecules, such as DNA helicases (MCM4 and MCM7), as well as ZEB1, Vimentin and SNAI1, which contributed to tumor cell growth and epithelial-to-mesenchymal transition (EMT) process." (PMID 35790743, 2022). "In addition, five of the genes that we identified in this study, CPEB4, DUSP6, NF1, RNF4, and STAT2, were previously proposed as prognostic markers for NSCLC, whereas changes in the expression of MCM4 and WEE1 were associated with lung cancer development." (PMID 27418131, 2016). "However, few reports focused on the role of MCM4 on lung cancer, especially LUAD." (PMID 37817427, 2023). "Using the Lung Cancer Explorer (LCE) portal, MCM4 was found to be significantly overexpressed in both LUAD (SMD = 1.79) and LUSC (SMD = 3.68), suggesting its relevance across NSCLC subtypes." (PMID 40564876, 2025). "MCM4 is highly expressed in LUAD and knockdown MCM4 leads to suppressed growth in the lung cancer cells." (PMID 35790743, 2022). "GSEA for different expression levels of MCM4, MCM5 and MCM8 indicated that significant correlation of the genes with lung cancer progression and survival." (PMID 31323040, 2019).
lung adenocarcinoma (10 papers, 2021 to 2025). A carcinoma that arises from the lung and is characterized by the presence of malignant glandular epithelial cells. "Here, this study mainly focused on the expression of MCM4 and its values in lung adenocarcinoma (LUAD)." (PMID 37817427, 2023). "Our recent study showed that siRNA-mediated knockdown of MCM4 attenuated the aggressiveness of lung adenocarcinoma cells." (PMID 33801812, 2021). "Interestingly, a recent study has demonstrated that a relationship between EGFR and MCM4 is observed in lung adenocarcinoma." (PMID 37737200, 2023). "In addition, the down-regulation of MCM4 inhibited the growth, migration and invasion of lung adenocarcinoma cells." (PMID 34993142, 2021). "However, the biological role and clinical significance of MCM4 in lung adenocarcinoma remain largely unexplored, and whether it plays a role in LUAD metastasis has not been systematically evaluated." (PMID 40564876, 2025). "Interestingly, while many of the genes are highly connected, four of the HUB genes upregulated during lung adenocarcinoma (MCM10, MCM4, GINS2 and CD45) are predicted to interact nearly independently through direct binding mechanisms." (PMID 33604163, 2021).